FBXO33 (F-box protein 33)
Description:
Substrate recognition component of a SCF (SKP1-CUL1-F-box protein) E3 ubiquitin-protein ligase complex which mediates the ubiquitination and subsequent proteasomal degradation of target proteins. Probably recognizes and binds to phosphorylated target proteins. Recognizes YBX1 (By similarity).
Synonyms: FBX33; BMND12; c14_5247
Tractability: PROTAC: ubiquitination databases record sites on it.
Gene: Protein-coding gene on chromosome 14 (39,397,684 to 39,432,466, reverse strand). Ensembl gene ENSG00000165355.
Subcellular location (Human Protein Atlas): Nucleoplasm
Gene Ontology:
Molecular function: protein binding
Biological process: positive regulation of protein ubiquitination; SCF-dependent proteasomal ubiquitin-dependent protein catabolic process; protein ubiquitination
Cellular component: SCF ubiquitin ligase complex
Genetic constraint (gnomAD): Loss-of-function variants: 17 observed, 37.32 expected, observed/expected ratio (o/e) 0.46, 90% interval 0.31 to 0.68. The synonymous counts are far from expectation, so gnomAD's model fits this gene poorly and the ratio says little. Missense variants: 648 observed, 655.43 expected, observed/expected ratio (o/e) 0.99, 90% interval 0.93 to 1.05. Synonymous variants: 324 observed, 265.05 expected, observed/expected ratio (o/e) 1.22, 90% interval 1.12 to 1.34.
Homologues: Orthologues: chimpanzee FBXO33 (99% identical), pig FBXO33 (97% identical), rabbit FBXO33 (96% identical), rat Fbxo33 (94% identical), mouse Fbxo33 (94% identical), macaque FBXO33 (93% identical), tropical clawed frog fbxo33 (72% identical), zebrafish fbxo33 (52% identical), Drosophila melanogaster CG4911 (21% identical).
Diseases named in the same sentence as FBXO33 in open-access papers:
FBXO33 is named in the same sentence as 11 diseases in open-access papers, as found by Europe PMC text mining. Sharing a sentence is not in itself a finding about the gene and the disease. The quoted sentences say what the papers report.
gallbladder cancer (2 papers, 2025).
Blindness (1 paper, 2018). Blindness is the condition of lacking visual perception defined as a profound reduction in visual perception. "The strongest eQTL target of rs8014839, CTAGE5 together with FBXO33 has been associated on a genome-wide level with an optic neuropathy (glaucoma) in animals as one of the leading causes of blindness." (PMID 30111286, 2018).
cancer (2 papers, 2023 to 2025). A tumor composed of atypical neoplastic, often pleomorphic cells that invade other tissues. "The findings confirmed that FBXO33 expression was elevated in cancer tissues compared to adjacent tissues." (PMID 40021626, 2025). "There are no relevant reports of ZNF79, PRICKLE3, RPAP1, ABHD8, and FBXO33 in cancer, and more research is still needed." (PMID 37274025, 2023).
tumor (2 papers, 2025). "Recent studies have identified that FBXO33, a member of the F-box family, acts as a tumor suppressor by promoting ubiquitination and degradation of MYC, thereby inhibiting metastasis in non-small cell lung cancer." (PMID 40021626, 2025). "In contrast, tumors in the Flag-FBXO33 group were larger and heavier, suggesting that FBXO33 overexpression promoted tumor growth." (PMID 40021626, 2025). "Tumors in the sh-FBXO33 group were smaller and lighter compared to those in the sh-Scr group, indicating that FBXO33 knockdown inhibited GBC tumor growth." (PMID 40021626, 2025). "Additionally, IHC staining was performed to assess protein expression levels of FBXO33 in 82 paired GBC tumor and adjacent tissues." (PMID 40021626, 2025). "However, the role of FBXO33 in other tumor types, including GBC, remains unclear." (PMID 40021626, 2025).
FBXO33 also shares sentences with these, for which no sentence is quoted: alcohol dependence (1 paper); autism spectrum disorder (1); bipolar disorder (1); gallstones (1); glaucoma (1); Hypertension (1); Optic neuropathy (1).